ARPC1A (actin related protein 2/3 complex subunit 1A)
Description:
Probably functions as a component of the Arp2/3 complex which is involved in regulation of actin polymerization and together with an activating nucleation-promoting factor (NPF) mediates the formation of branched actin networks.
Synonyms: SOP2L; SOP2Hs; Arc40; HEL-68; HEL-S-307
Tractability: Small molecule: a structure with a bound ligand is known. PROTAC: ubiquitination databases record sites on it; its protein half-life has been measured.
Gene: Protein-coding gene on chromosome 7 (99,325,880 to 99,366,267, forward strand). Ensembl gene ENSG00000241685.
Subcellular location: Cytoplasm, cytoskeleton; Nucleus
Subcellular location (Human Protein Atlas): Cell Junctions; Cytosol
Pathways (Reactome):
Developmental Biology: EPHB-mediated forward signaling
Disease: FCGR3A-mediated phagocytosis
Immune System: Regulation of actin dynamics for phagocytic cup formation
Signal Transduction: RHO GTPases Activate WASPs and WAVEs
Vesicle-mediated transport: Clathrin-mediated endocytosis
Gene Ontology:
Molecular function: protein binding; actin binding; actin filament binding
Biological process: Arp2/3 complex-mediated actin nucleation; actin cytoskeleton organization; cortical actin cytoskeleton organization
Cellular component: Arp2/3 protein complex; extracellular exosome; actin cytoskeleton; cytosol; nucleus; site of double-strand break; cytoskeleton; glutamatergic synapse; muscle cell projection membrane; synapse
Genetic constraint (gnomAD): Loss-of-function variants: 8 observed, 46.57 expected, observed/expected ratio (o/e) 0.17, 90% interval 0.1 to 0.31. The upper end of that interval is the gene's LOEUF score, 0.31, which puts it in group 1 of 6, group 1 being the genes least tolerant of losing a copy. Missense variants: 286 observed, 495.42 expected, observed/expected ratio (o/e) 0.58, 90% interval 0.52 to 0.64. Synonymous variants: 152 observed, 174.73 expected, observed/expected ratio (o/e) 0.87, 90% interval 0.76 to 1.
Homologues: Orthologues: chimpanzee ARPC1A (100% identical), dog ARPC1A (100% identical), guinea pig ARPC1A (100% identical), mouse Arpc1a (99% identical), pig ARPC1A (97% identical), rabbit ARPC1A (96% identical), rat Arpc1a (94% identical), macaque ARPC1A (92% identical), tropical clawed frog arpc1a (91% identical), zebrafish arpc1a (91% identical), Caenorhabditis elegans arx-3 (58% identical), Drosophila melanogaster Arpc1 (57% identical). Paralogues in human: ARPC1B (68% identical).